Y_RNA (Y RNA )
Gene: Miscellaneous RNA gene on chromosome 14 (67,617,302 to 67,617,415, reverse strand). Ensembl gene ENSG00000201529.
Homologues: Orthologues: macaque Y_RNA (96% identical). Paralogues in human: RNY1 (86% identical), Y_RNA (84% identical), Y_RNA (83% identical), RNY1P8 (82% identical), Y_RNA (82% identical), RNY1P11 (81% identical), Y_RNA (81% identical), Y_RNA (80% identical), Y_RNA (79% identical), RNY1P2 (78% identical), RNY1P5 (78% identical), RNY1P7 (78% identical), and 92 more.